HAX1 (HCLS1 associated protein X-1)
Diseases named in the same sentence as HAX1 in open-access papers (continued):
Sharing a sentence is not in itself a finding about the gene and the disease.
tumor (23 papers, 2010 to 2026). "In tumor sites, hematopoietic substrate-1-associated protein X-1 (HAX-1) is highly expressed during neovascularization." (PMID 33663535, 2021). "Analyses of HAX1 protein levels in groups stratified according to known prognostic factors showed that the values of the cytoplasmic and total HAX1 signal were positively associated with tumor grade (resp)." (PMID 31093284, 2019). "Overexpression was detected, as expected, in the cytoplasm, but also in the nuclei of tumor cells, which is inconsistent with previous findings, associating HAX-1 with cytoplasmic structures (ER and lammelipodia,; ER and mitochondria,; mitochondria." (PMID 20196840, 2010). "It is important to note that, Hax-1 exists as many as 7 alternative splicing forms, and these splicing variants may play important roles in development or tumor formation." (PMID 22827267, 2012). "Future studies examining the co-expression of RPS4X, MCL1, and HAX1 in clinical tumor samples, as well as functional studies in patient-derived models, will be essential to validate the potential oncogenic role of RPS4X." (PMID 41154579, 2025). "Immunohistochemistry (IHC) staining on orthotopic tumor showed that EIF3H KD led to reduced levels of EIF3H, HAX1 and pERK1/2, and repressed cell proliferation (Ki67 staining), while HAX1 overexpression reversed these impacts caused by EIF3H KD." (PMID 38514606, 2024). "It is conceivable that impact of HAX1 in RAS-RAF-MEK-ERK pathway can override tightly regulated mechanisms to facilitate tumor proliferation and metastasis." (PMID 38514606, 2024). "In the orthotopic CRC model, EIF3H knockdown decreases orthotopic tumor growth, and attenuates liver and lung metastasis, while HAX1 can rescue these phenomena under EIF3H knockdown." (PMID 38514606, 2024). "More and more researches have revealed that the expression of HAX-1 is high in a variety of malignancies, affecting tumor cell proliferation, migration, and apoptosis." (PMID 35602302, 2022). "Here, our team was the first to reveal that HAX-1 knockout affects the viability, migration, and tumor cell spheroidizing ability of UM cells." (PMID 35602302, 2022). "There was a decrease of PCNA expression in Lenti‐shHAX1 groups which indicated HAX1 knockdown inhibited the tumour growth." (PMID 34755451, 2021). "We also confirmed that elevated HAX-1 expression levels are closely correlated with tumor development." (PMID 33663535, 2021). "The analysis revealed also the correlation of HAX1 overexpression with tumor grade, which is consistent with our previous and current IHC results." (PMID 31093284, 2019). "Undeniably, additional novel, specific oncogenic roles for HAX-1 will help us to clarify its functions when encapsulated and released into the environment by the tumor." (PMID 26871467, 2016). "To confirm the effects of HAX-1 on tumor progression, we next investigated the function of HAX-1 in vivo." (PMID 26871467, 2016). "In agreement with our data above, exosomes with high level of HAX-1 protein accelerated tumor growth." (PMID 26871467, 2016). "As expected, the size of the tumor masses from the HAX-1-knockdown mice were significantly smaller compared with those fron the mice in the control group." (PMID 26062578, 2015). "The results revealed that downregulating the expression of HAX-1 in the SW480 cells suppressed tumor growth in vivo in the mice xenograft model." (PMID 26062578, 2015). "Hax-1 is a multifunctional protein, which is involved in diverse cellular signaling pathways including tumor cell survival and migration." (PMID 25053987, 2014). "Collectively these studies point to a novel, but yet to be resolved role for Hax-1 in tumor cell migration and metastasis." (PMID 25053987, 2014). "The analysis of other prognostic markers demonstrated a significant relation between HAX1 expression level and tumor size, which confirms the results obtained from the cDNA panel." (PMID 20196840, 2010).
tumor (continued). "Intensive HAX-1 staining was observed not only in the cytoplasm, but also in the nuclei of the tumor cells." (PMID 20196840, 2010). "The involvement of HAX-1 in processes crucial to carcinogenesis as well as demonstration of its overexpression in several tumor cell lines provides strong arguments for a detailed analysis of its role in neoplastic transformation and metastasis." (PMID 20196840, 2010). "Importantly, combination of Wnt inhibitor and RAF1/MEK inhibitor can suppress the tumor growth of patient-derived xenografts (PDXs) that have EIF3H/HAX1 overexpression." (PMID 38514606, 2024). "The correlation of HAX1 expression with other genes can be analyzed in expression databases created using high-throughput methods applied to patient samples from many different neoplasms." (PMID 36230905, 2022). "On the other hand, HAX1 overexpression was documented in several neoplasms." (PMID 36230905, 2022). "In addition, NPC-Exo carries the oncogenic HS1-associated protein X-1 (HAX-1), which can accelerate NPC tumor growth and angiogenesis." (PMID 29617291, 2018). "Similarly, the lenti-miR-125a trasfected tumor samples exhibited lower levels of HAX-1 compared with the lenti-control transfected tumor samples in vivo." (PMID 27880721, 2016). "Growth curves showed reduced tumor volumes in xenografts with silenced HAX-1 expression." (PMID 26871467, 2016). "Moreover, mice injected with NPC-exosomes had higher levels of HAX-1 in the xenograft tumor than mice injected with exosomes from healthy donors." (PMID 26871467, 2016). "While all these studies point to a determinant role for Hax-1 in critical signaling pathways involved in cell growth, differentiation, apoptosis, tumorigenesis and tumor cell migration, the functional role played by Hax-1 in these diverse cellular responses are far from clear." (PMID 25053987, 2014). "Our results indicate the relation of HAX1 expression to tumor size, stage and grade of the disease but more detailed analysis is needed to confirm if the observed relationships are in any way connected to a potential role for HAX-1 in metastasis." (PMID 20196840, 2010). "Since the inhibition of apoptosis and the induction of cell invasiveness are crucial for carcinogenesis, it is logical to expect that HAX-1 overexpression in neoplastic cells should contribute to tumor resistance to apoptosis as well as to the enhancement of metastatic potential." (PMID 20196840, 2010). "HAX-1 up-regulation was detected in most of the tumor samples." (PMID 20196840, 2010). "Importantly, HAX1 overexpression increased tumorigenicity and demonstrated strong metastatic capability; therefore, it could reverse reduced tumor growth and restore compromised lung and liver metastasis caused by EIF3H KD." (PMID 38514606, 2024). "Gene ontology analysis demonstrated that genes differentially expressed in HAX1 KO (including genes involved in ribosome biogenesis and translation) are also enriched in a subset of genes whose expression correlates with HAX1 expression in four analyzed neoplasms." (PMID 36230905, 2022). "To confirm these findings, we examined the expression of HAX-1 in freshly obtained NPC tissues and non-tumor nasopharyngeal tissues." (PMID 26871467, 2016). "We found that NPC-derived exosomes are enriched in HAX-1 and accelerate NPC tumor growth and angiogenesis in vitro and in vivo." (PMID 26871467, 2016). "Additionally, the high concentration of HAX1 gene expression was related to the TNM stage, lymphatic metastasis, and tumor size." (PMID 36290366, 2022). "The NUP85, HAX1, GNPDA1 and HDLBP protein levels were significantly elevated in tumor tissues compared to normal samples, while GPD1 was significantly down-regulated in tumor tissues." (PMID 33663535, 2021).
tumor (continued). "As the preceding results indicated that the miR-223/HAX-1 axis regulates the TRAIL-induced apoptosis in TNBCSCs, we next investigated the responses of TNBCSCs to some other anti-tumor chemotherapeutic agents such as doxorubicin and cisplatin when they were transfected with miR-223." (PMID 27618431, 2016). "The results of the present study demonstrated that the expression levels of HAX-1 were significantly upregulated in the tumor specimens, compared with the adjacent noncancerous tissues, which was concordant with the findings of previous studies." (PMID 26062578, 2015). "The expression levels of HAX-1 in the individual tumor and noncancerous tissue sections from the 60 patients with CRC were detected using immunohistochemistry." (PMID 26062578, 2015). "In addition, NUP85, HAX1, GNPDA1 and HDLBP exhibited elevated mRNA expression levels in GI tumor tissues when compared to the adjacent non-tumor tissues, whereas GPD1 expression was suppressed in GI tumor tissues compared to the non-tumor tissues." (PMID 33663535, 2021).
infection (4 papers, 2018 to 2023). The state of being infected such as from the introduction of a foreign agent such as serum, vaccine, antigenic substance or organism. "The interaction of EspO1 and HAX-1 was further confirmed in a targeted FLAG pull-down by immunoblotting for HAX-1 following infection in HT-29 and HeLa cells." (PMID 34021690, 2021). "We also showed that when HAX-1 was reduced in shRNA knockdown lung epithelial cells, the activation of procaspase-9 was initiated earlier at 8 hrs post infection, which, however, was only achieved much later (at 24 hrs) in normal cells." (PMID 29576744, 2018). "Interestingly, HAX1 expression in host cells was significantly upregulated in response to CCHFV infection even at low doses (MOI = 0.1 or 0.3)." (PMID 37963884, 2023). "Therefore, during both infection and ectopic expression EspO protects cells from cell death by interacting with HAX-1." (PMID 34021690, 2021). "Since HAX-1 is suppressive to apoptosis through binding to procaspase-9, an association of HAX-1 and PB1-F2 during the infection may sequester PB1-F2 from activating procaspase-9, resulting in decreased activation of caspase-9." (PMID 29576744, 2018). "Prior to infection, 6–8-week-old female C57BL/6 mice were transduced with the HAX1-targeting or control shRNA expression vectors." (PMID 37963884, 2023). "This suggests that EspO1 inhibits cell detachment during infection in a HAX-1-dependent/ILK independent manner, while NleH1 and NleF operate independently of HAX-1." (PMID 34021690, 2021). "Both HAX-1 and ILK were further confirmed as EspO1-interacting proteins during infection using T3SS-delivered EspO1." (PMID 34021690, 2021). "Obviously, it would be of great importance to study the localization of HAX-1, PB1-F2, and PA in the context of infection." (PMID 29563290, 2018). "Accordingly, we investigated if EspO1 could also prevent cell detachment following infection of HeLa cells with ICC303 and if so, whether this was dependent on HAX-1." (PMID 34021690, 2021). "Using non-targeted pull downs during infection, we confirmed that HAX-1 was part of the EspO1 interactome when EspO is delivered by the T3SS during infection." (PMID 34021690, 2021). "In HAX-1 knockdown A549 cells, the replication of AIV H9N2 was suppressed in parallel to the activation of caspase-3 activation, which increased at the early stage of infection." (PMID 29576744, 2018). "As shown in the analysis of invasion to cells, HAX1 did not notably affect the infection efficiency of the pseudovirus harboring CCHFV glycoproteins (VSV△G/GFP-CG) that was prepared in advance, suggesting HAX1 likely does not affect CCHFV glycoprotein-directed invasion." (PMID 37963884, 2023). "To evaluate the activation of apoptosis without HAX-1, we infected HAX-1kd and HAX-1wt cells with H9N2 (wt) virus at an MOI of 1 and analyzed the cleavage status of caspase-9 and caspase-3 during the course of infection." (PMID 29576744, 2018).
bacterial infection (1 paper, 2021). "We have established that EspO1 exerts its anti-apoptotic effect both during ectopic expression and bacterial infection, in a HAX-1-dependent manner." (PMID 34021690, 2021).
connective tissue disorder (1 paper, 2018). A disease involving the connective tissue. "This rare condition in SCN can be explained by severe infections and sheath weakness, a connective tissue disorder caused by an HAX1 deficiency." (PMID 30598852, 2018).
GI tumor (1 paper, 2021). "We identified five novel glycolysis-associated genes (NUP85, GPD1, HAX1, GNPDA1, and HDLBP) in GI tumor and normal tissues." (PMID 33663535, 2021).
HAX1 also shares sentences with these, for which no sentence is quoted: esophageal squamous cell carcinoma (3 papers); cervical carcinoma (2); genetic disease (2); agranulocytosis (1); Barth syndrome (1); chronic granulomatous disease (1); chronic myeloid leukemia (1); Cohen syndrome (1); Cyclic neutropenia (1); cyst (1); epilepsy (1); esophageal cancer (1); esophageal neoplasms (1); Friedreich ataxia (1); Glucose intolerance (1); glycogen storage disease (1); glycogen storage disease type Ib (1); Glycogen storage diseases type 1b (1); hearing loss (1); Insulin resistance (1); invasive ductal carcinoma (1); invasive lobular carcinoma (1); lymphoma (1); mesothelioma (1); myocardial infarction (1); neurodevelopmental disorder (1); non-small cell lung carcinoma (1); oral squamous cell carcinoma (1); primary immunodeficiencies (1); Sepsis (1).
A further 2 diseases each share a sentence with HAX1 in 1 paper.